CCL2 (C-C motif chemokine ligand 2)
Diseases named in the same sentence as CCL2 in open-access papers (continued):
Sharing a sentence is not in itself a finding about the gene and the disease.
prostate carcinoma (continued). "Tumor associated macrophages (TAMs) secrete pro-inflammatory cytokines such as CCL5 and CCL2 which greatly affect the progression of prostate cancer and prostate cancer metastasis." (PMID 36836690, 2023). "CCL2 is reported to directly induce PC cell line proliferation and migration in prostate cancer via phosphoinositide-3-kinase (PI3K)/serine-threonine kinase (Akt) signaling activation." (PMID 36289628, 2022). "It has been reported that the inhibition of AR signaling promotes CCL2 secretion in prostate cancer cells." (PMID 36077785, 2022). "CCL2 can enhance the migration and invasion ability of prostate cancer cells, as well as induce the invasion of liver cancer cells." (PMID 35464849, 2022). "CCL2 also accelerates tumor development by increasing angiogenesis in several kinds of cancers, such as hepatocellular carcinoma, prostate cancer, esophageal squamous carcinoma, and gastric carcinoma." (PMID 36077785, 2022). "Anti-CCL2 monoclonal antibodies also markedly inhibited the prostate-cancer bone metastasis progression in intracardiac and intra-tibial models." (PMID 36289628, 2022). "The cut-off CCL2 value was set at 320 pg/mL, but CCL2 has been found to increase with prostate-cancer progression in the prior paper." (PMID 36289628, 2022). "CCL2 promotes bone metastasis in experimental models of prostate cancer while its inhibition hinders TAM recruitment and correlates with reduced tumor burden." (PMID 34803925, 2021). "At a signaling level, activation of the PI3 kinase/Akt pathway was found to be vital for the CCL2-mediated proliferative effects of prostate cancer epithelial cells." (PMID 34804061, 2021). "CCL2 was shown to promote migration and invasion of prostate cancer cells and to facilitate the formation of osteoclasts." (PMID 34064589, 2021). "It has been reported that ECs played a major role in the secretion of CCL2 during bone metastasis of prostate cancer." (PMID 33403387, 2021). "Another report showed that cabazitaxel-resistant prostate cancer cell lines strongly secrete CCL2 and are thus highly involved in cabazitaxel resistance." (PMID 34445235, 2021). "Androgen receptor knockdown in prostate cancer promotes cancer cell migration/invasion via CCL2- dependent STAT3 activation and EMT pathways." (PMID 33986252, 2021). "Bone marrow endothelial cells were shown to secrete considerably higher levels of CCL2 compared to aortic and dermal endothelial cells, leading to preferential recruitment of prostate cancer cells to the bone and local support of their proliferation." (PMID 34503058, 2021). "CCL2 is a prominent modulator of bone metastatic growth of prostate cancer, it promotes cell proliferation, invasion, and migration by binding to CCR2 in both autocrine and paracrine manners." (PMID 33514011, 2021). "CCL2 is increased by treatment with the chemotherapeutic drug docetaxel and protects prostate cancer cells from docetaxel-induced toxicity but when combined with CCL2 blockade, docetaxel had striking impact on tumor suppression." (PMID 34803925, 2021). "Taken together, these data suggest that HOXA11-AS is an upstream regulator of CCL2/CCR2 signaling in both prostate cancer cells and osteoblastic cells." (PMID 33514011, 2021). "Prostate cancer cells also produce CCL2 to recruit macrophages/TAMs or osteoclasts that assist with pro-tumorigenic lesion formation." (PMID 34803925, 2021). "In contrast, TR4 was demonstrated to promote prostate cancer metastasis via CCL2 and EZH2 signaling." (PMID 34616769, 2021). "We demonstrated that HOXA11-AS secreted from prostate cancer PC3 cells was able to modify CCL2 and IBSP expression levels in SaOS2 osteoblastic cells in a paracrine manner." (PMID 33514011, 2021). "In prostate cancer studies, CCL2 overexpresses in the tumor microenvironment and acts as an important role in tumorigenesis and invasion." (PMID 34638796, 2021).
prostate carcinoma (continued). "Carlumab usage, which is an anti-CCL2 monoclonal antibody, has successfully decreased the tumor growth in prostate cancer." (PMID 34281293, 2021). "CCL2 expression has been confirmed in multiple human prostate cancer cell lines, such as LNCaP, C4-2, and PC3." (PMID 34445235, 2021). "In animal models, CCL2 blocking has been effective on glioma, colon cancer, prostate cancer, and melanoma." (PMID 34281293, 2021). "The inhibition of CCL2 has been demonstrated in order to improve sensitivity to docetaxel in prostate cancer cell in vitro and the overexpression of CCL2 can enhance cell proliferation in prostate cancer cells that were treated with docetaxel." (PMID 33076397, 2020). "CCL2 was also able to stimulate prostate cancer cells to extravasate into the bone through a layer of bone marrow endothelial cells partially by the activation of the small GTPase Rac through the actin-associated protein PCNT1." (PMID 32471499, 2020). "Prostate cancer cells express higher amounts of CCL2, exhibiting both autocrine and paracrine functions." (PMID 32585812, 2020). "In another study to determine the role of CCL2/CCR2 axis in growth of prostate cancer in the bone, knocking down CCR2 abrogated tumor invasiveness." (PMID 32585812, 2020). "A recent study reported that the coffee compound kahweol acetate and cafestol can reduce not only CCL2 secretion but also CCR2 expression on prostate cancer cells." (PMID 33297571, 2020). "Initially, CCL2 was focused on and studied as a key molecule in the migration and proliferation of prostate cancer cells." (PMID 33297571, 2020). "The blocking of AR signaling can drive increased inflammation in prostate cancer cells by the induced expression of CCL2, promoting prostate cancer progression via activation of the STAT3 signaling pathway and recruitment of TAMs." (PMID 33076397, 2020). "In prostate cancer, CCL2 is particularly up-regulated in bone metastasis, and promotes tumor growth and progression." (PMID 32824865, 2020). "In breast and prostate cancers elevated CCL2 serum levels correlate with advanced stages of the disease, suggesting a link between CCL2 expression and bone metastasis." (PMID 32326073, 2020). "In advanced prostate cancer, CCL2 expression was also notably higher in the metastatic tumor-bone microenvironment compared with that in bone marrow adjacent to the tumor as measured by cytokine arrays." (PMID 32471499, 2020). "The outcome of prostate cancer patients with CCL2-positive tissues was significantly worse with lower survival time than those patients with CCL2-negative tissues." (PMID 33297571, 2020). "Further, CCL2-induced prostate cancer cell chemotaxis was abolished by a CCR2 antagonist, which confirmed that CCR2 is the functional receptor of CCL2." (PMID 32471499, 2020). "The up-regulation of CCL2/CCR2 and varied immune conditions in prostate cancer, are associated with cancer advancement, metastasis, and relapse." (PMID 32471499, 2020). "For example, chemokine (C-C motif) ligand 2 (CCL2, also known as MCP1) was found to protect human PC3 prostate cancer cells from undergoing autophagic death via PI3K/AKT-dependent survivin upregulations." (PMID 32019552, 2020). "Prostate cancer cells LNCaP, C4-2B, PC-3, and VCaP produce higher amounts of CCL2 than primary prostate epithelial cells." (PMID 32471499, 2020). "The inhibition of CCL2 activity with neutralizing antibodies in an in-vivo model of prostate cancer metastasis decreased overall tumor burden." (PMID 32585812, 2020). "CCL2 directly stimulates prostate cancer cell proliferation and migration via activation of the phosphatidylinositol 3-kinase (PI3K)/ protein kinase B (Akt) signaling pathway and Rac GTPase, respectively." (PMID 33297571, 2020). "Additional evidence suggests the potential for CCL2 inhibition as a target for overcoming chemotherapeutic resistance in prostate cancer bone metastases." (PMID 33076397, 2020).
prostate carcinoma (continued). "Again, the development of prostate cancer cells was found to be promoted through PTHrP-induced CCL2 production by osteoblasts and HBME cells." (PMID 32585812, 2020). "CCL2 contributes to the acquisition of resistance to taxane chemotherapies such as docetaxel and cabazitaxel in prostate cancer cells." (PMID 33297571, 2020). "CCL2 is also reported as a key chemokine for bone metastasis and cancer drug resistance in prostate cancer." (PMID 32971847, 2020). "Bone marrow endothelial cells express high levels of CCL2 in order to recruit prostate cancer cells and TAMs to the bone, which is the primary site for prostate cancer metastases." (PMID 33076397, 2020). "CCL2 is also important in the perineural invasion of cervical cancer and prostate cancer, due to the expression of CCL2 in the nervous tissue." (PMID 33182504, 2020). "CCL2 is involved in the malignant progression of prostate cancer, and the IL1RN was shown to increase the proliferation of normal prostate epithelial cells." (PMID 33322099, 2020). "Our earlier studies showed that human chemokine CCL2 contributes to malignant progression of prostate cancer (e.g., proliferation and invasion)." (PMID 32244522, 2020). "Up-regulation of CCL2 induced by metastatic prostate cancer cells promotes the infiltration of TAMs." (PMID 32971847, 2020). "An in-vivo metastasis study in which CCL2 was overexpressed in PC3-luc cells demonstrated how CCL2 affects prostate cancer bone metastasis." (PMID 32585812, 2020). "CCL2 [also known as MCP1 (monocyte chemoattractant protein 1)] is highly expressed in prostate cancer cells with high metastatic potential." (PMID 32971847, 2020). "Upregulation of serum CCL2 levels enhanced the tumor growth of prostate cancer LNCaP xenografts in high-fat diet fed mice." (PMID 32824865, 2020). "Human prostate carcinoma-associated fibroblasts and prostate cancer cells orchestrate and enhance TAM and MDSC recruitment to prostate tumors as well as M2-like TAM differentiation by the chemokines CCL2, CXCL12, and IL-6 during cancer progression." (PMID 32824865, 2020). "Both CCR2 and CCR4 were observed to be expressed in human prostate cancer cell lines and prostate cancer tissues; furthermore, in vitro co-culture of prostate cancer cells and macrophages resulted in increased CCL2 and CCR2 levels in prostate cancer cells." (PMID 30871130, 2019). "Previous studies have shown that CCL2 secreted by prostate cancer cells confer a survival advantage to these cells." (PMID 31287009, 2019). "Cytokine array analysis of conditioned media from siAR and scr cells revealed increased CCL2 expression in siAR cells, supporting a potential role for prostate cancer cell-derived CCL2 in mediating local inflammatory responses during suppression of AR." (PMID 30871130, 2019). "CCL2 is reported to play a potential role in stimulating capillary network formation of human microvascular endothelial cells in the microenvironment of prostate cancer." (PMID 30871130, 2019). "Technically, several studies have reported that bioluminescence imaging (BLI) reveals slow tumor growth after anti-CCL2 treatment with docetaxel in mouse prostate cancer." (PMID 31366997, 2019). "In conclusion, DT displays radiosensitization and antimigration effects in prostate cancer cells by inducing DNA damage and inhibiting CCL2 secretion." (PMID 29386061, 2018). "DT displays radiosensitization and antimigration effects in prostate cancer cells by inducing DNA damage and inhibiting CCL2 secretion." (PMID 29386061, 2018). "In our previous studies, DT reduced the secretion of CCL2 by both lung cancer cells and prostate cancer cells, yet the effect of the combined therapy on CCL2 secretion by prostate cancer cells is unclear." (PMID 29386061, 2018).
prostate carcinoma (continued). "Previously, we have shown that I3C and DIM, through androgen-dependent pathways, modulate the interaction between prostate cancer cells and macrophages by regulating the production of chemokine CCL2 by prostate cancer cells." (PMID 29364159, 2018). "Our results suggest that CCL2 is among the cytokines that control the migration ability of DT- or combination-treated prostate cancer cells, and that DT and combined treatment inhibit the migration of prostate cancer cells through their effects on CCL2." (PMID 29386061, 2018). "CCL2 recruits prostate cancer epithelial cells to the bone microenvironment and regulates their rate of proliferation." (PMID 29386061, 2018). "We subsequently used ELISA to examine the effects of different treatments on the secretion of IL-8 or CCL2 by prostate cancer cells." (PMID 29386061, 2018). "In the bone metastasis of prostate cancer, tumor-derived PTHrP induces CCL2 from osteoblasts, which acts on the tumor cells to induce VEGF secretion and therefore promotes angiogenesis." (PMID 29642534, 2018). "In tissue sections of human colon and prostate carcinoma, nitrated CCL2 was detected using nanobodies." (PMID 30233568, 2018). "In previous studies, increased CCL2 expression in prostate cancer cells encouraged metastasis through macrophage recruitment." (PMID 29386061, 2018). "Mechanistically, DT and the combination treatment reduced the secretion of chemokine (C-C Motif) Ligand 2 (CCL2) from prostate cancer cells." (PMID 29386061, 2018). "Further, prostate cancer cell lines (PC-3 and VCaP) elevated bone marrow CCL2 levels in a mouse xenograft model." (PMID 28424660, 2017). "In vitro, we observed the effects of DT on the interaction between macrophages and prostate cancer cells by interrupting the CCL2 pathway." (PMID 28157698, 2017). "Because the conditioned medium of THP-1 cells can activate the migration of prostate cancer cells and contain CCL2, we used this medium as our model." (PMID 28157698, 2017). "CCL2 is highly produced by bone marrow osteoblasts, endothelial cells and stromal cells as well as tumor cells, including breast cancer, prostate cancer and myeloma cells." (PMID 28467800, 2017). "Taken together, PTHrP enhances CCL2 expression in osteoblasts, signifying the role of prostate cancer cell-derived PTHrP in bone metastasis, likely via enhanced CCL2 expression." (PMID 28424660, 2017). "We also discovered that DT treatment inhibited the protein expression of CCL2 in the medium obtained from the prostate cancer cells and macrophage coculture in vitro system." (PMID 28157698, 2017). "Previous studies have also indicated that increased CCL2 expression in prostate cancer cells encouraged metastasis through macrophage recruitment." (PMID 28157698, 2017). "In another study, the authors found that autocrine and paracrine functions of CCL2 are required for prostate cancer growth and invasion, and treatment with a CCR2 antagonist reduced the CCL2-mediated prostate cancer growth and invasion." (PMID 28424660, 2017). "Previously, we reported that the serum CCL2 level in patients with prostate cancer was clearly predictive of the time taken by the tumor to become castration resistant and of overall and prostate cancer-specific survivals." (PMID 28039457, 2017). "CCL2 recruits prostate cancer cells to the bone microenvironment and activates their proliferation rate." (PMID 28157698, 2017). "In vitro co-culture of monocyte-lineage cells with prostate cancer cells induce higher expression of CCL2, which promotes the expressions of CCR2 and CCR4 in prostate cancer cells." (PMID 28039457, 2017). "Mechanistically, DT both diminished the ability of prostate cancer cells to recruit macrophages and reduced the secretion of chemokine (C-C motif) ligand 2 (CCL2) from both macrophages and prostate cancer cells in a dose-dependent manner." (PMID 28157698, 2017).
prostate carcinoma (continued). "It has been previously demonstrated that CCL2 promotes prostate cancer cell proliferation, migration, and survival via Akt-activation-dependent mechanisms." (PMID 28039457, 2017). "CCR2 and CCR4 antagonists clearly inhibited the migration ability of prostate cancer cells, which was induced by CCL2 and CCL17/CCL22." (PMID 28039457, 2017). "When prostate cancer cells were treated with human recombinant CCL2, migration was induced in a dose-dependent manner." (PMID 28039457, 2017). "Our previous study demonstrated that DT inhibits the tumor-promoting ability of macrophages in prostate cancer through the inhibition of the CCL2/STAT3 axis." (PMID 29207614, 2017). "Our in vitro approach of enriching for prostate cancer cells with higher migration potential showed that CCL2 activated cellular migration." (PMID 26701731, 2016). "This is in keeping with the observation in a prostate cancer metastasis model that CCL2 inhibition must be sustained to maintain tumor regression, and further questions the effects of CNTO 888 or MLN1202 treatment withdrawal in clinical trials." (PMID 26885690, 2016). "Further, CCL2 induces resistance to anti-androgens via interaction between prostate cancer cells and TAM." (PMID 26701731, 2016). "Patients with CCL2 ≥ 320 pg/mL had worse overall survival and prostate cancer -specific survival than those with CCL2 < 320 pg/mL." (PMID 26701731, 2016). "Among those altered cytokines, we focused on the CCL2, a key cytokine that can regulate prostate cancer progression yet its expression was suppressed by ASC-J9®." (PMID 27564257, 2016). "We further investigated molecular mechanisms by which AR inhibits CCL2 secretion in AR-positive human prostate cancer cell lines." (PMID 26701731, 2016). "Our present data indicate that CCL2 induces prostate cancer cell migration in vitro not only under ADT conditions but also without the suppression of androgen/AR signaling." (PMID 26701731, 2016). "CCL2 was identified from meta analyses of gene expression datasets on prostate tumorigenesis as a primary driver of prostate cancer development consistent with the experimental findings summarized above." (PMID 26885690, 2016). "In the present study, we investigated the validity of chemokine (CC motif) ligand 2 (CCL2) as a biomarker complementary to PSA in prostate cancer diagnosis and prognosis." (PMID 26701731, 2016). "Initially, CCL2 was reported to promote prostate cancer metastasis through the recruitment of macrophages using PC-3 cells that did not express AR." (PMID 26701731, 2016). "Immunohistochemical analysis of tissue specimens suggests that patients with prostate cancer with high CCL2 expression in their tumors had worse OS and shorter time to recurrence after prostatectomy than those with low CCL2 expression." (PMID 26701731, 2016). "Although androgen/androgen receptor (AR) signaling promotes prostate cancer progression, suppression of AR signaling induces chemokine (CC motif) ligand 2 (CCL2), which enables prostate cancer cells to gain metastatic potential." (PMID 26701731, 2016). "The expression of CCL2 correlated with a poor prognosis and metastatic disease in patients with several types of cancer, including breast and prostate cancer." (PMID 25695619, 2015). "The monocyte-induced prostate cancer cell invasion was inhibited by CCL2 neutralizing antibodies and by the CCR2 inhibitor, RS102895." (PMID 26317041, 2015). "In co-cultures of prostate cancer cell lines with monocyte-lineage cells, (C-C motif) ligand 2 (CCL2) levels were significantly increased when compared with monocytes or cancer cells cultured alone." (PMID 26317041, 2015). "This study demonstrated that PC-3 prostate cancer cell NF-κB activity was also stimulated by the co-cultures and CCL2 treatment." (PMID 26317041, 2015).